BRAF (B-Raf proto-oncogene, serine/threonine kinase)
Diseases named in the same sentence as BRAF in open-access papers (continued):
Sharing a sentence is not in itself a finding about the gene and the disease.
cancer (continued). "These BRAF wild type cancers are typically MSS and frequently show chromosomal instability (CIN), the presence of which has been correlated with a poor prognosis in these cancers." (PMID 24651849, 2014). "ARAF encodes a scaffold that stabilizes BRAF: CRAF heterodimers and regulates RAF signaling; and specific inhibitors have been successful in phase I/II clinical trials in cancer patients." (PMID 25007077, 2014). "In cancer patients, dual inhibition of BRAF/MEK/ERK1/2 and PI3K/AKT/mTOR pathways is in phase I clinical trials." (PMID 24970815, 2014). "Here we show that the novel RAF/MEK inhibitor CH5126766 suppresses the cell growth of RAS-mutated cells as well as BRAF-mutated cells, which raises the possibility that CH5126766 is promising for the therapy against RAS-mutated malignant tumors." (PMID 25422890, 2014). "A recent study identified the basis of different activity of MEK inhibitors in BRAF versus KRAS mutant cancers." (PMID 24722523, 2014). "KRAS mutations were present in 28% BRAFwt/MSS cancers and the mutual exclusivity of KRAS with BRAF mutations was confirmed." (PMID 24651849, 2014). "Trametinib is an inhibitor of MEK, which acts downstream of BRAF and is also registered for BRAF mutant cancers." (PMID 24651269, 2014). "We used this model system to study cancer cells traits depending on B-RafV600E and to identify agents selectively targeting BRAF-mutant cells." (PMID 24885690, 2014). "Out of three RAF isoforms (ARAF, BRAF, and CRAF), BRAF is the most potent contributor to the MAPK pathway and is the only isoform commonly mutated in human cancer." (PMID 24673746, 2014). "Although most BRAF mutants display elevated kinase activity compared to the wild type, four cancer-derived mutants have reduced kinase activity: G466E, G466V, G596R, and D594V." (PMID 24817905, 2014). "In approximately half of these BRAF mutant cancers, CIMP related methylation and silencing of the DNA mismatch repair gene, MLH1, results in widespread frameshift mutations known as microsatellite instability (MSI)." (PMID 24651849, 2014). "miR-96 is located at chromosome 7q32, a region containing several oncogenes including MET and BRAF and frequently amplified in cancers." (PMID 25333253, 2014). "BRAF mutant/MSI cancers have been well characterized and show typical molecular and clinical features including an excellent patient outcome." (PMID 24651849, 2014). "The majority of patients (75%) had microsatellite-stable cancers with wild-type BRAF gene (72% in males and 77.9% in females)." (PMID 25268611, 2014). "The majority of sporadic CRC are BRAF wild type and arise from conventional adenomas that follow a well defined pathway of molecular events leading to cancer." (PMID 24651849, 2014). "The prevalence of oncogenic BRAF V600E mutations in several solid tumors has led to the development of anti-cancer agents that specifically inhibit BRAF V600E." (PMID 23717811, 2013). "Alternatively, it is possible that there is a reduced propensity for pathologic DNA hypermethylation in the Asian population studied, thus reducing the ability of BRAF mutant precursor lesions to progress towards cancer." (PMID 24066160, 2013). "This classification essentially retains the MSI+ set of cancers as a separate group, but with the addition of BRAF-mutant MSI– cancers." (PMID 23165447, 2013). "In summary, these data clearly support the specific cellular selectivity of dabrafenib for activated mutant BRAF in cancer cells." (PMID 23844038, 2013).
cancer (continued). "Several mouse genetic models of BRAF-induced cancer have been developed, either by activation of latent endogenous mutant alleles or through thyroid-specific overexpression." (PMID 23372702, 2013). "Patients with BRAF mutant tumors had an average age of 72, compared to the average age of 65 for the entire cohort, and the cancer was located more commonly in the proximal colon (65% compared with 49% for complete cohort)." (PMID 24066160, 2013). "The KIAA1549 gene is known for its fusion with BRAF gene involved in the MAPK/ERKs signaling pathway which is thought to play a pivotal role in melanoma as well as other cancer development." (PMID 23641255, 2013). "Also, mutational analysis for KRAS and BRAF discloses some possible interactions between type I and type II pathway and could be useful in detection of small proportion of high-grade carcinomas arising through type I pathway, with possible diverse clinical behavior and specific therapy requirements." (PMID 23388101, 2013). "As expected there were too few CIMP high cancers in the BRAF wild type/MSS cohort to allow for comparisons between cohorts." (PMID 23110075, 2012). "In contrast, the BRAF wild type/MSS cancers had the highest frequency of instability on the 17p arm, and the least at 8p and 5q." (PMID 23110075, 2012). "BRAF wild type cancers are typically microsatellite stable (MSS) and instead acquire chromosomal instability (CIN)." (PMID 23110075, 2012). "BRAF and NRAS mutations occur frequently in benign and malignant neoplasm’s that arise from melanocytes in epithelial structures." (PMID 25562798, 2012). "Cigarette smoking was associated with CIMP and BRAF mutant tumors, odds ratio (OR) 2.85 (95% CI 1.53–5.29), and MSI cancer OR 3.43 (95% CI 1.57–7.50)." (PMID 22792460, 2012). "Findings from this and our previous study, suggest that BRAF mutant/MSS cancers form an aggressive cancer subgroup with distinct clinical and molecular features." (PMID 23110075, 2012). "Many of the CIN positive BRAF mutant/MSS cancers showed CIMP and thus this study challenges the belief that CIN and CIMP are mutually exclusive." (PMID 23110075, 2012). "In accordance with previous findings, the BRAF mutant/MSS cancers conferred poorer survival rates compared to the BRAF wild type cancers, irrespective of the presence or not of CIN (p = 0.001)." (PMID 23110075, 2012). "It provides additional evidence that BRAF mutant/MSS cancers are fundamentally different to their MSI counterparts although they both potentially arise from BRAF mutant serrated polyps." (PMID 23110075, 2012). "The overall mutation frequency of KRAS, BRAF and PIK3CA in our HNSCC samples was lower than reported for other cancers." (PMID 22994622, 2012). "BRAF mutant cancers that are MSS, typically present at an advanced stage and have a particularly poor prognosis." (PMID 23110075, 2012). "The BRAF mutant/MSS cancers had the greatest degree of CIN on the 8p chromosomal arm, and the least at the 18q region." (PMID 23110075, 2012). "This study, for the first time, reports a high frequency of CIN in the aggressive BRAF mutant/MSS cancers thought to progress via the serrated neoplastic pathway." (PMID 23110075, 2012). "The lack of association reported in these studies likely reflects the low frequency of CIMP in BRAF wild type cancers." (PMID 23110075, 2012). "This study reports that a high level of CIN is evident in BRAF mutant/MSS cancers and this demonstrates at least one mechanism of genomic instability by which these cancers form and progress." (PMID 23110075, 2012). "CIN was frequent in BRAF mutant/MSS cancers (41/57, 72%), which was comparable to the rate found in BRAF wild type/MSS cancers (74/90, 82%)." (PMID 23110075, 2012). "An inverse relationship between CIN and CIMP has previously been observed in a predominantly BRAF wild type cancer cohort where only 9 BRAF mutant/MSS cancers were investigated." (PMID 23110075, 2012).
cancer (continued). "This was compared to a randomly selected control cohort of 90 MSS, BRAF wild type cancers (BRAFwt/MSS)." (PMID 23110075, 2012). "In the present study, CIMP occurred in only 4% of BRAF wild type cancers, precluding the meaningful analysis of CIMP correlating with CIN in this subgroup." (PMID 23110075, 2012). "By identifying 60 BRAF mutant/MSS cancers from a large series of 1052 patients, the necessary power was attained to examine frequency of CIN in relation to other clinical and molecular variables." (PMID 23110075, 2012). "MSI affects genomic integrity at the DNA level and develops at the polyp/carcinoma transition of BRAF mutant serrated polyps which silence MLH1 by DNA methylation through the CIMP phenotype." (PMID 23110075, 2012). "Mutation of either RAS or BRAF, or PIK3CA and PTEN, which are considered as initial mutations of the differentiated carcinomas are found in the majority of ATC." (PMID 23115614, 2012). "We examined the clinical characteristics and outcomes of patients with mutant (mut) BRAF advanced cancer referred to phase 1 clinic." (PMID 22039425, 2011). "Five BRAF mutations and one KRAS c61 mutation were observed among 11 MSI-H cancers when unmatched cases were included (P = 0.007)." (PMID 21457162, 2011). "Cancer cells with mutant KRAS or BRAF have higher levels of GLUT1 RNA and protein expression and higher rates of glucose uptake and glycolysis which allows the cells to survive in conditions of low glucose." (PMID 21826239, 2011). "Previous studies that have examined the relationship between BRAF and KRAS mutations in a wide range of colonic polyp and cancer tissue have found a mutually exclusive distribution of these mutations." (PMID 21347319, 2011). "Using data in the Catalog of Somatic Mutations in Cancer (COSMIC) database, we have demonstrated that our method detects well-known clusters of activating mutations in KRAS, BRAF, PI3K, and β-catenin." (PMID 20053295, 2010). "For example, the triarylimidazole SB590885 and the difluorophenylsulfonamine PLX4720 display excellent selectivity for BRAF in vitro and preferentially inhibit BRAF mutant cancer cell proliferation." (PMID 20141835, 2010). "It inhibits V600EBRAF at 2 nM, is ineffective against a panel of 64 other protein kinases, and preferentially blocks BRAF mutant cancer cell proliferation." (PMID 20141835, 2010). "A small inhibitory RNA construct targeting the expression of both wild-type BRAF and BRAF V600E induced a comparable reduction of viability in both wild-type and BRAF V600E mutant cancer cells." (PMID 20628483, 2010). "Published studies of the clinical validity of BRAF p.Val600Glu testing were retrospective analyses of patients treated with cetuximab or panitumumab at cancer treatment centers or a cohort of patients that had been in one of three clinical trials." (PMID 20972475, 2010). "In summary, we show that inhibition of BRAF in RAS mutant cancer cells leads to MEK hyperactivation through CRAF." (PMID 20141835, 2010). "In cancer, RAS and BRAF mutations arise de novo in somatic tissues, but germ-line RAS, RAF and MEK mutations have also recently been identified as causing a series of syndromes that share overlapping clinical features." (PMID 20230482, 2010). "In line with this, increased expression of CRAF can mediate acquired resistance to pan-RAF drugs in BRAF mutant cancer cells in vitro, establishing that CRAF can mediate resistance under some circumstances." (PMID 20141835, 2010). "Previous reports and Cancer Genome Project by Sanger Institute have extensively characterised LKB1 mutations in NSCLC cell lines with KRAS and BRAF mutations, but LKB1 status of EGFR mutant NSCLC cell lines has not been extensively analysed." (PMID 18594528, 2008).
cancer (continued). "Like most cancer-causing mutations in BRAF, biochemical studies have determined that most novel CFC B-Raf mutant proteins have increased kinase activity relative to the kinase activity of wild-type B-Raf." (PMID 18060073, 2007). "In this study, we report novel BRAF mutations in exon 4 and exon 12 and also report the first mutation in MEK1 associated with human cancer." (PMID 18060073, 2007). "BRAF, which encodes an RAF family member in the downstream pathway of RAS, is somatically mutated in a number of human cancers." (PMID 14612909, 2003). "Such differential occurrences of BRAF and RAS mutation in some human cancers led us to analyse BRAF mutation in NHL in which RAS mutation is known to be an uncommon event." (PMID 14612909, 2003). "In contrast, BRAF gene mutations have been found in 5%–15% of CRC cases; are more common in older patients, women, and right‐sided colon cancers, and are characterized by a high frequency of advanced cancer, resistance to chemotherapy, and poor prognosis." (PMID 40548293, 2026). "Notably, these strategies have shown promising potential in reversing drug resistance to BRAF inhibitors, sorafenib, 5-fluorouracil (5-FU) and other agents, providing novel strategies for pan-cancer therapy." (PMID 41816347, 2026). "Furthermore, pan-cancer analyses implicate the BRAF25 signature in poor prognosis across diverse BRAF-driven malignancies." (PMID 41648055, 2026). "There were no high-risk cancers identified in patients with isolated BRAF mutation (benign: n = 10 [34.5%], ATA low risk: n = 19 [65.5%]), and the most common isolated mutation was K601E (n = 17, 45.9%) which had a 58.8% ROM (all ATA low risk)." (PMID 40075589, 2025). "The development of BRAF inhibitors has been a notable advance in the treatment of various cancers." (PMID 40869231, 2025). "These cases were recorded in the cancer registry of the Pathology Department at the National Institute of Oncology/Sabrata between 2019 and 2020 and were referred for further assessment of KRAS/BRAF mutations at the department’s molecular unit." (PMID 41439081, 2025). "Dabrafenib, a BRAF inhibitor, and trametinib, a MEK inhibitor, work synergistically to inhibit the Mitogen-Activated Protein Kinase/Extracellular signal-Regulated Kinase (MAPK/ERK) pathway, which is crucial for the growth and survival of BRAF-mutant cancer cells." (PMID 41562808, 2025). "CMS data were available for 114 class 1, 4 class 2, and 28 class 3 BRAF-mutant cancers." (PMID 39751654, 2025). "In addition, ARID1A, BRAF, and PIK3CA mutations seemed to increase in the metastatic cohort, compared with TCGA and in-house primary cancer cohorts (all p < 0.05)." (PMID 39941707, 2025). "In addition, several HDACs were identified, which also play a crucial role in the drug resistance of BRAF-mutant cancers." (PMID 39935431, 2025). "Additionally, cancer-specific mutations within BRAF disrupt its interaction with SPOP, allowing BRAF to evade SPOP-mediated ubiquitination." (PMID 40521202, 2025). "In those reports, several cancers that were RAS-negative turned out to carry BRAF, TERT or RET/PTC changes, showing that they could have been flagged by a broader gene panel." (PMID 41450928, 2025). "Given the observed interaction with BRAF status, we speculate CMV and other CVIs may influence the development of other cancers in a more nuanced, cancer-specific and potentially mutation-dependent, manner." (PMID 40269332, 2025). "Similar to key mutations in oncoproteins (G12 in KRAS, V600 in BRAF, or T41 in β-catenin), we investigated whether mutations at T980 occur in FASN across various cancers." (PMID 40684943, 2025).
cancer (continued). "There were no high-risk cancers identified in patients with isolated BRAF mutations (benign: n = 10 [34.5%], ATA low risk: n = 19 [65.5%])." (PMID 40075589, 2025). "This means that Antrocin is a potential anti-cancer drug, as it interacts with BRAF/MEK/PI3K with equally lower Gibbs free energies compared to the standard inhibitors and a short binding distance to the interacting amino acid, indicating its strong binding affinity to this oncogenic signature." (PMID 41009348, 2025). "Collectively, these findings elucidate an ARF6-dependent mechanism of BRAF oncoprotein synthesis that may be exploited in BRAFV600E driven cancers as a therapeutic vulnerability." (PMID 40909781, 2025). "Subsequent studies using EGFR and BRAF inhibition with vemurafenib and cetuximab in Class 1 BRAF-mutant CRC revealed mild improvements in ORR, but still did achieve the clinical efficacy of single-agent BRAF inhibition in other BRAF-mutated cancer types." (PMID 41294686, 2025). "Because tumors bearing a BRAF V600E mutation are oncogenically addicted to this hyperactivated signaling cascade, it was postulated, and later confirmed, that small-molecule inhibitors targeting BRAF V600E offer an effective therapeutic strategy for these cancers." (PMID 40332392, 2025). "Four samples with TSHR mutations (two with TSHR only and two with BRAF V600E/TSHR) were confirmed to be one malignant tumor, one benign tumor, and two lack of surgical pathology." (PMID 40586006, 2025). "The combination of atypical BRAF and other atypical Ras mutations (in KRAS, NRAS, or NF1) is consistent with a “mini-driver” model in which some cancers acquire sufficient Ras activation through a two-step process rather than a single “hit” at BRAFV600E or one of the common KRAS hotspots." (PMID 39751654, 2025). "In addition to overcoming resistance to BRAF inhibitors in melanoma cells and EGFR-tyrosine kinase inhibitor resistance in non–small lung cancer cells, HA15 lowered viability of a wide range of cancer cells, including those bearing various KRAS mutations." (PMID 40699920, 2025). "Co-occurrence with the BRAF V600E mutation amplifies TERT expression by activating ETS transcription factors, which bind to newly created ETS sites in the mutated TERT promoter, driving cancer cell immortality." (PMID 40332222, 2025). "Given the increasing use of BRAF/MEKi in different cancer types, real-life safety data are crucial to identify known as well as novel toxicities occurring in patients outside clinical trials, which usually include highly selected populations without baseline significant comorbidities." (PMID 40507236, 2025). "Thus, apoptosis-correlated factors are promising drug targets in BRAF-mutant cancers, but can also have limited activities in BRAF/MEK inhibitor-resistant cancers requiring further actions to eliminate resistant cells." (PMID 39935431, 2025). "The incidence and type of BRAF fusion vary among different cancers." (PMID 40111124, 2025). "The type of BRAF mutation, and the presence of concomitant RNF43 mutation, may explain some of the differences in cancer behaviour." (PMID 41002577, 2025). "BRAF Class I mutations possess strong kinase activity compared to BRAF Class II and Class III and are solely found at the V600 locus, making this mutation class a target for new cancer therapies." (PMID 41179283, 2025). "In addition, treatment with clinical antgonists of kinases involved in cancer such as BRAF or c-KIT induces OXPHOS-addiction that limits drug efficacy and simultaneously induces sensitivity to OXPHOS inhibition as combination therapy." (PMID 40597978, 2025). "Our previous study found that KRAS and BRAF mutations in ctDNA are not predictive of cancer relapse, suggesting that the use of these mutations in ctDNA alone is insufficient for recurrence prediction." (PMID 40698441, 2025).